STEAP1 (STEAP family member 1)
Diseases named in the same sentence as STEAP1 in open-access papers (continued):
Sharing a sentence is not in itself a finding about the gene and the disease.
metastatic prostate carcinoma (5 papers, 2022 to 2025). A carcinoma that arises from the prostate gland and has spread to other anatomic sites. "The adoptive transfer of STEAP1 CAR T cells was associated with prolonged peripheral persistence and either disease eradication or substantial tumor growth inhibition in mouse metastatic prostate cancer models." (PMID 37762648, 2023). "We first set out to determine the pattern and extent of STEAP1 expression relative to PSMA in advanced metastatic prostate cancer." (PMID 37041154, 2023). "B7-H3(CD276), PSMA(FOLH1) and STEAP1 are co-expressed in metastatic prostate cancers." (PMID 40964329, 2025). "Six-Transmembrane Epithelial Antigen of the Prostate 1 (STEAP1) is a surface antigen that is expressed in over 80% of metastatic prostate cancer, higher than the 60% positivity on an immunochemistry study conducted at Fred Hutchinson Cancer Center using a H score of 30 as a cutoff for positivity." (PMID 37762648, 2023). "In order to investigate the efficacy of STEAP1 CAR T cells targeting metastatic cancer, we established a metastatic prostate cancer mouse model." (PMID 35860008, 2022).
endometrial carcinoma (4 papers, 2020 to 2022). A malignant tumor arising from the epithelium that lines the cavity of the uterine body. "In contrast, some studies have indicated that STEAP1 upregulation is associated with reduced growth and migration of endometrial cancer cells." (PMID 32265985, 2020). "STEAP1 downregulation is associated with the degree of malignancy, tumor differentiation, and lymph node metastasis in endometrial cancer." (PMID 32265985, 2020). "However, STEAP1 downregulation has been reported in endometrial carcinoma, and STEAP1 upregulation is associated with a better patient prognosis rather than STEAP1 downregulation." (PMID 32265985, 2020). "In contrast, STEAP1 was upregulated in the normal human endometrium and downregulated in most endometrial cancer tissue specimens." (PMID 32265985, 2020). "Previous study has shown that STEAP1 is downregulated in endometrial carcinoma and that knockdown of STEAP1 could promote cell proliferation, migration, invasion and epithelial to mesenchymal transition (EMT)." (PMID 36685847, 2022). "Furthermore, the prognosis of patients with endometrial cancer with high STEAP1 expression levels was significantly better than that of patients with low STEAP1 expression levels." (PMID 32265985, 2020).
lymph node metastasis (3 papers, 2020 to 2023). "The mean STEAP1 H-score in bone (193; 95% CI 171 to 215) was significantly higher than in lymph node metastases (difference −48; 95% CI −21 to −76; p < 0.001) and significantly higher than in visceral metastases (difference −59; 95% CI −42 to −77; p < 0.001)." (PMID 37041154, 2023). "Low STEAP1 expression was positively correlated with high clinical stage and positive lymph node metastasis in patients." (PMID 35346237, 2022). "STEAP1 upregulation in the tumor tissue specimens of 40 LUAD patients significantly correlated with an advanced T stage and lymph node metastasis (LNM) (P < 0.05)." (PMID 32265985, 2020).
osteosarcoma (3 papers, 2022 to 2025). A usually aggressive malignant bone-forming mesenchymal neoplasm, predominantly affecting adolescents and young adults. "The relationship between STEAP1 and osteosarcoma will be discussed in other study." (PMID 36316642, 2022). "The interaction between EFEMP1 and STEAP1 facilitates the initiation of Wnt/β-catenin and TGF-β/Smad2/3 axes, leading to the induction of EMT, thereby promoting the infiltration and migration of osteosarcoma cells." (PMID 39822989, 2025).
prostate adenocarcinoma (3 papers, 2021 to 2025). "In an attempt to better understand whether DNA methylation status may have an impact on STEAP1 gene expression, the Prostate Adenocarcinoma dataset was analyzed from The Cancer Genome Atlas (TCGA, Cell 2015), accessed through the cBioPortal." (PMID 34833128, 2021). "Interestingly, canonical prostate adenocarcinoma cell-surface targets KLK2 and STEAP1 had significantly lower expression in the LumB versus LumA samples, and STEAP2 also had a trend toward lower expression in LumB, in contrast to FOLH1, which was highly expressed in both luminal CTC phenotypes." (PMID 39912912, 2025). "Considering that the results above suggest a negative association between histone deacetylation and STEAP1 mRNA expression, we intended to analyze the association between STEAP1 mRNA expression and HDAC mRNA expression, using the Prostate Adenocarcinoma (TCGA, Cell 2015) dataset." (PMID 34833128, 2021). "STEAP1 is minimally expressed in normal tissue, highly expressed in prostate adenocarcinoma (PRAD), and is absent in NEPC." (PMID 40759791, 2025).
small cell lung carcinoma (3 papers, 2025 to 2026). Small cell lung cancer (SCLC) is a highly aggressive malignant neoplasm, accounting for 10-15% of lung cancer cases, characterized byrapid growth, and early metastasis. "Recent advances seen with tebentafusp in metastatic uveal melanoma and tarlatamab in small-cell lung cancer have validated the approach and driven a rapidly expanding pipeline targeting other tumor associated antigens such as STEAP1, MUC16, and PRAME among others." (PMID 41964902, 2026).
thyroid cancer (3 papers, 2011 to 2022). "STEAP1 expression was positively correlated to immune molecules especially in thyroid carcinoma and negatively especially in uveal melanoma." (PMID 35313641, 2022).
carcinoid tumor (2 papers, 2021 to 2022). A slow growing neuroendocrine tumor, composed of uniform, round, or polygonal cells having monotonous, centrally located nuclei and small nucleoli, infrequent mitoses, and no necrosis. "Acting as EMT transcription factors, EGFR and STEAP1 were proved to be highly expressed among pulmonary neuroendocrine carcinomas and downregulated in carcinoid tumors, which suggested that STEAP1 may have interaction with EGFR pathway in the process of EMT." (PMID 35313641, 2022).
Ewing family tumors (2 papers, 2016 to 2025). "Similarly, Ewing family tumors with mRNA expression of a combination of several markers, including STEAP1, also indicate an association between high STEAP1 expression and poor patient survival." (PMID 27104516, 2016). "In Ewing family tumors, elevated STEAP1 expression correlates with diminished metastasis-free survival (MFS), defined as the interval from treatment initiation to the first occurrence of localized lymph node or distant organ metastasis." (PMID 40299363, 2025).
gastric tumors (2 papers, 2022). "In gastric tumors, the upregulation of STEAP1 increased cell proliferation, migration, and invasion." (PMID 35216235, 2022).
glioma (2 papers, 2021 to 2022). A benign or malignant brain and spinal cord tumor that arises from glial cells (astrocytes, oligodendrocytes, ependymal cells). "Interestingly, a strong positive correlation of STEAP1 and STEAP2 average expression of pan-cancer was identified in our study including glioma and other different tumor tissues." (PMID 35313641, 2022). "Survival differences for DSS demonstrated that patients with higher STEAP1 expression in ACC, glioma, KICH, KIRP, LAML, LUAD, and PAAD experienced poor prognosis whereas patients in the high-expression group of STEAP1 with BRCA, ESCA, KIRC, LIHC, UCEC, and UVM had better survival outcomes." (PMID 35313641, 2022). "However, the functional role of STEAP1 and STEAP2 in glioma has not yet been established." (PMID 33790946, 2021).
metastatic disease (2 papers, 2021 to 2023). "Differential gene expression analysis and subsequent GSEA comparing 22Rv1 metastatic tumors from mice treated with STEAP1-BBζ CAR T cell therapy to those treated with untransduced T cells showed negative enrichment of pathways involved in MHC, cytotoxic lymphocytes, and T cell activation." (PMID 37041154, 2023).
adenomyosis (1 paper, 2022). The growth of endometrial tissue inside the muscular wall of the uterine corpus. "Downregulation of STEAP1 may be related to abnormal immune infiltration in the eutopic endometrium of women with adenomyosis." (PMID 36685847, 2022). "The downregulation of STEAP1 was also noted in our study in the endometrium of women with adenomyosis, which may lead to abnormal endometrial cell proliferation and EMT induction, both of which play important roles in the etiology of adenomyosis." (PMID 36685847, 2022). "The expression levels of STEAP1, GLT8D2, NME5, and TOMM20 were downregulated and showed statistical significance (p < 0.05) in the adenomyosis group compared with those in the control group." (PMID 36685847, 2022). "The microarray dataset analysis revealed that the expression levels of TMEM97, GLT8D2, NME5, STEAP1, and TOMM20 were significantly downregulated in the endometrium of women with adenomyosis compared with those in the control group (p < 0.05)." (PMID 36685847, 2022). "This study identified STEAP1, TOMM20, GLT8D2, and NME5 as potential biomarkers for adenomyosis." (PMID 36685847, 2022). "In this study, we found that the expression of STEAP1 was positively correlated with the resting CD4 memory T-cell, M1 macrophages and gamma-delta T-cell and negatively correlated with monocytes and CD8 T-cell in adenomyosis." (PMID 36685847, 2022).
Autoimmunity (1 paper, 2022). The occurrence of an immune reaction against the organism's own cells or tissues. "Since STEAP1 is a self-antigen, one concern about these vaccines is that they may trigger autoimmunity." (PMID 36011027, 2022).
Cirrhosis (1 paper, 2024). A chronic disorder of the liver in which liver tissue becomes scarred and is partially replaced by regenerative nodules and fibrotic tissue resulting in loss of liver function. "To further explore the association between STEAP1 and STEAP4 with the development of HCC, we analyzed the correlation between their expression with some particular etiology (alcohol consumption, hepatitis, non-alcoholic fatty liver disease) and liver fibrosis (including cirrhosis) in HCC." (PMID 38191397, 2024).
colorectal tumor (1 paper, 2016). "In the present study, STEAP1 expression was detected mainly in colorectal tumor tissue." (PMID 27104516, 2016). "The IHC staining of STEAP1 protein in colorectal tumor tissue revealed no nuclear expression of STEAP1, and at least 99% of the specimens had membranocytoplasmic STEAP1 expression." (PMID 27104516, 2016). "We recently observed that STEAP1 (six transmembrane epithelial antigen of the prostate 1) is overexpressed at the RNA level in circulating colorectal tumor cells (data not published), which raises the possibility that STEAP1 might be associated with tumor metastasis." (PMID 27104516, 2016).
epilepsy (1 paper, 2021). A brain disorder characterized by episodes of abnormally increased neuronal discharge resulting in transient episodes of sensory or motor neurological dysfunction, or psychic dysfunction. "Furthermore, the hub genes of each AD- and epilepsy-associated GCM were captured, including TRPC1, C2ORF40, NR3C1, KIAA0368, MMT00043109, STEAP1, MSX1, KL, and CLIC6." (PMID 34697589, 2021). "Furthermore, the hub genes of AD- and epilepsy-associated GCMs were captured by weighted key driver analysis (wKDA), including TRPC1, C2ORF40, NR3C1, KIAA0368, MMT00043109, STEAP1, MSX1, KL, and CLIC6." (PMID 34697589, 2021).
hepatocellular carcinoma (1 paper, 2023). A malignant tumor that arises from hepatocytes. "We had also previously investigated the biological mechanisms of STEAP1 in hepatocellular carcinoma (HCC)." (PMID 37909017, 2023).
liver fibrosis (1 paper, 2024). "The results showed that STEAP1, STEAP4, and risk score were not correlated with specific etiology, while STEAP1 and risk score were significantly positively correlated with liver fibrosis both in TCGA and GSE14520." (PMID 38191397, 2024).
papillary thyroid carcinomas (1 paper, 2014). "As far as the papillary thyroid carcinomas are concerned, FOS, FOSB and EGR1 genes were down-regulated, like CBX7, while SPP1, SPINK1 and STEAP1 were up-regulated." (PMID 24865347, 2014).
sarcoma (1 paper, 2014). A usually aggressive malignant neoplasm of the soft tissue or bone. "We selected CCND1, MTA1, STEAP1, CDH2, CDH11, and CDT2 genes that are known to be involved in metastatic spread in several sarcoma subtypes, and their abnormal expression in tumors correlates specifically with poor prognosis in ES patients." (PMID 25008066, 2014).
Sepsis (1 paper, 2024). Sepsis is defined as life-threatening organ dysfunction caused by a dysregulated host response to infection. "Thus, targeting STEAP1 and SP-NK1R signaling pathways, along with addressing ferroptosis, may provide therapeutic benefits in mitigating sepsis-induced ALI by reducing ferroptosis and associated inflammation." (PMID 39671383, 2024).
squamous cell carcinoma (1 paper, 2022). A carcinoma arising from squamous epithelial cells. "The expression of STEAP1 in highly differentiated squamous cell carcinoma is significantly lower than that in poorly differentiated squamous cell carcinoma." (PMID 35346237, 2022).
tumor (70 papers, 2011 to 2026). "STEAP1 is associated with tumor invasiveness and progression, which makes it an attractive target for circumventing tumor escape." (PMID 40270044, 2025). "Intratumoral treatment with STEAP1-BBζ CAR T cells was associated with significant tumor growth inhibition that was statistically significant by day 18 of treatment." (PMID 37041154, 2023). "Across multiple cancer forms, STEAP1 has been associated with tumor proliferation, progression, and invasiveness, including tumor invasion into the peritoneum." (PMID 36830995, 2023). "STEAP1 is an attractive target, as it is associated with tumor invasiveness and progression and only expressed at low levels in normal tissues, apart from the non-vital prostate gland." (PMID 35860008, 2022). "The associations of STEAP1 with tumor microenvironment, immune-infiltrating, and other immune-related biomarkers in different cancer types were also investigated based on online web servers and R program." (PMID 35313641, 2022). "The relationships of STEAP1 and biomarkers including tumor mutational burden (TMB), microsatellite instability (MSI), and stemness score as well as chemosensitivity were also illustrated." (PMID 35313641, 2022). "Across multiple cancer forms, STEAP1 has been associated with tumor proliferation, progression, and invasiveness." (PMID 35860008, 2022). "The binding of EWSFLI1 and NKX2.2 leads to very high expression of STEAP1 protein and causing a downstream increase in reactive oxygen species and related genes resulting in increased tumor invasiveness." (PMID 34073779, 2021). "In this study we designed over twenty DNA-encoded genetic adjuvants and tested their ability to enhance antigen-specific T cell responses to vaccination against two different tumor-associated antigens, STEAP1, and TERT." (PMID 32161596, 2020). "Independent to direct T cell engagement, vaccine formulation with Flt3L was associated with enhanced T cell responses to both tumor antigens by >2-fold (STEAP1: 2.67 fold; TERT: 2.7 fold)." (PMID 32161596, 2020). "The underlying mechanism whereby STEAP1 promotes circulating tumor cell formation and favorable prognosis needs further investigation." (PMID 27104516, 2016). "The overexpression of STEAP1 in tumor tissue seems to be associated with tumor malignancy, advanced grade, and poor prognosis." (PMID 27104516, 2016). "Some vaccination strategies using recombinant cDNA or viral vectors encoding mouse STEAP1 were successful in the induction of specific T cell responses, reduction of tumor growth and increase of survival in mouse models." (PMID 24213236, 2012). "Given the heterogeneity of antigen expression within tumors and over time, using TCEs against distinct targets (e.g., PSMA and STEAP1) could maximize tumor cell killing and mitigate the risk of antigen-loss escape." (PMID 40507301, 2025). "STEAP1 has been shown to be associated with tumor proliferation and progression." (PMID 38203757, 2024). "Indeed, STEAP1 has been appointed as a tumor-associated antigen that can function as a target for immunotherapy." (PMID 36768273, 2023). "STEAP1 is a hallmark of tumor invasiveness and an indicator of tumor responsiveness to therapy." (PMID 34073779, 2021). "However, it is unclear whether the loss of tumor STEAP1 expression is solely due to inherent tumor antigen heterogeneity or whether there is also adaptive downregulation of STEAP1 expression." (PMID 37041154, 2023). "46/58 (79.3%) mCRPC patients had at least one B7-H3 and STEAP1 positive tumor, 39/58 (67.2%) patients demonstrated at least one PSMA and STEAP1 positive tumor, and 34/58 (58.6%) patients harbored at least one B7-H3 and STEAP1 positive tumor." (PMID 40964329, 2025). "Building on this evolving immunotherapy landscape, six-transmembrane epithelial antigen of prostate 1 (STEAP1) has emerged as a promising immunotherapeutic target for mCRPC because of its selective tumor expression and accessible cell-surface localization." (PMID 40427518, 2025).